ENSG00000288715 (novel protein)
Synonyms: LOC128462377
Gene: Protein-coding gene on chromosome 16 (89,317,046 to 89,418,292, reverse strand). Ensembl gene ENSG00000288715.
Genetic constraint (gnomAD): Missense variants: 4 observed, 2.74 expected, observed/expected ratio (o/e) 1.46, 90% interval 0.63 to 1.93. Synonymous variants: 4 observed, 2.09 expected, observed/expected ratio (o/e) 1.91, 90% interval 0.73 to 1.95.